NRXN1 (neurexin 1)
Diseases named in the same sentence as NRXN1 in open-access papers (continued):
Sharing a sentence is not in itself a finding about the gene and the disease.
autism spectrum disorder (39 papers, 2009 to 2026). A spectrum of developmental disorders that includes autism, and Asperger syndrome. "NRXN1 deletions are identified as one of major rare risk factors for autism spectrum disorder (ASD) and other neurodevelopmental disorders." (PMID 34525970, 2021). "The PSD genes are extremely sequence conserved, and comprise scaffolding proteins, such as SHANK3 and NRXN1 genes, which are recurrently described with mutations in autism spectrum disorder and schizophrenia." (PMID 29531218, 2018). "Neurexins are neuronal cell surface protein and mutations of NRXN1 have been reported in patients with ID and autism spectrum disorder." (PMID 25902260, 2015). "For example, constitutional intragenic deletions within AUTS2, IMMP2L, and NRXN1 have been associated with autism spectrum disorder, intellectual disability, and psychiatric disorders." (PMID 25373142, 2015). "Importantly, Nrxn1 and Nrxn2, along with the Nrxn3, belong to the neurexin gene family, which has been linked to autism spectrum disorder (ASD), and epilepsy." (PMID 40608247, 2025). "Although all three neurexin genes have been associated with psychiatric disorders, NRXN1 variants account for the majority of disease burden, and NRXN1 variants appear to be the most frequently observed single-gene variants associated with autism spectrum disorder (ASD)." (PMID 36848371, 2023). "Copy number variations (CNVs) in the Neurexin 1 (NRXN1) gene, which encodes a presynaptic protein involved in neurotransmitter release, are some of the most frequently observed single-gene variants associated with autism spectrum disorder (ASD)." (PMID 36848371, 2023). "Interestingly, several genes (Adcyap1, Cntnap2, Grid1, Nrxn1, Nrxn3, Ucn, Tbx1, and Nr2e1), that are associated with disorders, stress response, social behaviors or autism spectrum disorders, are up-regulated specifically in the hippocampus of Del/+ mice." (PMID 28704368, 2017). "Deletions of one of the two copies of the Neurexin1 (NRXN1) gene are among the most common genetic anomalies in autism spectrum disorder (ASD), a neurodevelopmental condition afflicting 1 in every 44 children in the United States." (PMID 36848371, 2023). "For autism spectrum disorder, DGCR2, ARVCF, GNB1L, COMT, ZDHHC8, CHRNA7, and NRXN1 are candidate genes with various associated developmental defects." (PMID 37486921, 2023). "Studies have found that NRXN–NLGN links synaptic function to cognitive disease, and the mutations in the NRXN-1 and CNTN4 genes have been reported to cause autism spectrum disorders (ASD)." (PMID 36142685, 2022). "The phenotype of individuals with NRXN1 deletion is variable and includes autism spectrum disorders, mental retardation, language delays, and hypotonia." (PMID 20468056, 2010). "Intragenic rearrangements in NRXN1 in three families with autism spectrum disorder, developmental delay, and speech delay." (PMID 21034472, 2010). "Further research efforts to investigate such variable phenotypes associated with this unstable genomic region will provide further insight into the role of NRXN1 in the development of language delays, autism spectrum disorders, and physical features." (PMID 20468056, 2010). "Among them, we propose the isoform-dependent excitation-inhibition imbalance hypothesis of NRXN1 in autism spectrum disorder." (PMID 42211283, 2026). "Our data confirmed that NRXN1-related disorders mainly manifest with undistinctive dysmorphic features and neurological involvement consisting of more or less severe developmental delay/intellectual disability, autistic spectrum disorder, and epilepsy." (PMID 39655047, 2024). "The case of structural variants is especially interesting since several of the CNV loci identified in this study overlap with genomic regions previously implicated with developmental syndromes like autism spectrum disorder (2p16.3 [NRXN1 gene, Neurexin-1 protein]) or 22q11.2 deletion syndrome." (PMID 36370183, 2023).
autism spectrum disorder (continued). "Mutations in the NRXN1 gene (OMIM#600565) have been frequently detected in various neurodevelopmental disorders, particularly in individuals affected by severe developmental delay/intellectual disability (DD/ID), epileptic seizures, and autistic spectrum disorder (ASD)." (PMID 39655047, 2024). "In particular, a recurring observation is that of deletions in the very large neurexin-1 gene, and to these findings can be added the description of chromosomal rearrangements in or near the NRXN1 locus in two subjects with autism spectrum disorder." (PMID 20195527, 2010).
epilepsy (26 papers, 2010 to 2026). A brain disorder characterized by episodes of abnormally increased neuronal discharge resulting in transient episodes of sensory or motor neurological dysfunction, or psychic dysfunction. "For example, SCN2A, the causative gene for epilepsy-associated Dravet syndrome, is also a primary candidate gene for familial autism, while NRXN1 has been associated with epilepsy as well as autism, schizophrenia, and developmental disability." (PMID 31653223, 2019). "Neurexin-1 deletions result in an early onset epilepsy associated with severe recessive mental retardation." (PMID 30298130, 2018). "Microdeletions found only in GGE patients harboured a high proportion of genes previously associated with epilepsy and neuropsychiatric disorders (NRXN1, RBFOX1, PCDH7, KCNA2, EPM2A, RORB, PLCB1)." (PMID 25950944, 2015). "Our findings were consistent with prior literature, which found exonic mutations to be commonly associated with neuropsychiatric disease and NRXN1 mutations, as well as found a low prevalence of dysmorphic features and a relatively high frequency of seizure disorders." (PMID 38610832, 2024). "Mutations in neurexin-1, a neuroligin partner were also found in patients with epilepsy." (PMID 30298130, 2018). "These microdeletions affected 158 protein-coding RefSeq genes and exhibited an enrichment of genes previously associated with epilepsy (NRXN1, RBFOX1, PCDH7, KCNA2, EPM2A, RORB, PLCB1) and neuropsychiatric disorders (DPYD, CADM2, PARK2, GRM8, TSNARE1, TPH2, MACROD2)." (PMID 25950944, 2015). "Then, we analyzed and summarized the current research status of NRXN1 in other neuropsychiatric disorders, including attention-deficit hyperactivity disorder, insomnia, epilepsy, suicide, and depression." (PMID 42211283, 2026). "Genetically, heterozygous deletion of NRXN1 is commonly identified as a major rare risk among ASD, epilepsy, mental retardation, ADHD and schizophrenia." (PMID 34525970, 2021). "This indicates that the prevalence of epilepsy and breathing anomalies was distributed equally over the groups with a TCF4 deletion, TCF4 mutation and NRXN1 mutation." (PMID 27072915, 2016). "Deleterious mutations and microdeletions of the genes, NRXN1 and RBFOX1, have been reported in a large number of patients with a broad range of neuropsychiatric disorders, who were frequently also affected by epilepsy." (PMID 25950944, 2015). "In a former study we reported on homozygous or compound heterozygous defects in CNTNAP2 or NRXN1 in four patients with intellectual disability and epilepsy, resembling Pitt-Hopkins syndrome (PTHS, MIM #610954)." (PMID 21827697, 2011). "Moreover, other studies showed compound heterozygous NRXN1 deletions in patients with epilepsy, early developmental delay, and intellectual disability." (PMID 36737720, 2023). "NRXN1+/- deletions are associated with neurodevelopmental disorders including ASD and epilepsy." (PMID 34525970, 2021). "Omission of the NRXN1 gene is found in epilepsy, autism spectrum disorder (ASD), and schizophrenia." (PMID 33815100, 2021). "In our cohort, only one subject had a seizure disorder (subject 1), although his 5 Mb deletion encompassed the entire NRXN1 gene as well as the genes for follicle-stimulating hormone receptor (FSHR), luteinizing hormone/choriogonadotropin receptor (LHCGR), and Stoned B-like factor (STN1)." (PMID 20468056, 2010). "Moreover, aberrant calcium mechanisms induced by NRXN1 absence may be a potential target for stem cell therapy in epilepsy and its neuropsychiatric symptoms." (PMID 33815100, 2021). "In addition to Cacna1d, altered expression of gene NRXN1 may also play a role in epilepsy." (PMID 33815100, 2021).
Intellectual disability (24 papers, 2011 to 2024). "The microdeletion of NRXN1 at 2p16.3 is associated with several neurodevelopmental disorders and intellectual disability, too." (PMID 35008879, 2021). "We suggest that in addition to intellectual disability and psychiatric disease, NRXN1 deletion is a risk factor for a characteristic cognitive and dysmorphic profile." (PMID 25614873, 2014). "Expanding the observations from previous studies we now found that heterozygous defects in CNTNAP2 or NRXN1 can also be seen in association with severe intellectual disability." (PMID 21827697, 2011). "We found heterozygous defects in CNTNAP2 and NRXN1 in patients with severe intellectual disability, therefore expanding the clinical spectrum associated with monoallelic defects in either gene." (PMID 21827697, 2011). "We report on patients with heterozygous defects in CNTNAP2 or NRXN1 associated with severe intellectual disability, which has only been reported for recessive defects before." (PMID 21827697, 2011). "NRXN1 has also been associated with mental retardation, nicotine dependence, alcoholism and vertebral anomalies." (PMID 21687627, 2011). "To further delineate the clinical phenotype associated with potentially recessive defects in any of the two genes, we screened a group of patients with either severe intellectual disability resembling Pitt-Hopkins syndrome or the phenotypes caused by recessive CNTNAP2 or NRXN1 defects." (PMID 21827697, 2011). "A female (213684) with SCZ and a 549 kb deletion of NRXN1 also had moderate intellectual disability." (PMID 31602316, 2019). "In 8 further patients with variable intellectual disability and heterozygous deletions in either CNTNAP2 or NRXN1, the remaining allele was sequenced." (PMID 21827697, 2011). "For example, copy number variants (CNV) in NRXN1 are reported to be present in about 0.4% of autistic people, and SHANK3 in 0.05–0.7%, which increases to 2% in autistic people with moderate to profound intellectual disability." (PMID 37441676, 2023). "Patients suffering from mental retardation without autism or schizophrenia have also been found to harbor NRXN1 deletions." (PMID 26595880, 2015).
developmental delay (14 papers, 2010 to 2024). "Deletions in 1q24 (including the FMO group of genes and DNM3), 2q33.1 (SATB2), and 2p16.1 (NRXN1) are well-known variations associated with developmental delay (DD)." (PMID 37486921, 2023). "In a case series of germline deletions in NRXN1 in individuals with more severe developmental disorders, two subjects with severe developmental delay had inherited deletions of exons 1–5." (PMID 37601975, 2023). "A total of 144 deletions/loss were reported in DGV for the NRXN1 gene, among which 45 were reported in the CNV studies of developmental delay and the remaining 99 were from other CNV population studies." (PMID 29191242, 2017).
Pitt-Hopkins-like syndrome 2 (9 papers, 2015 to 2025). Any Pitt-Hopkins-like syndrome in which the cause of the disease is a mutation in the NRXN1 gene. "Bi-allelic NRXN1 loss-of-function, also referred to as Pitt-Hopkins-like syndrome 2 (OMIM #614325), represents the most severe end of the clinical spectrum associated with NRXN1 disruption." (PMID 41333154, 2025). "NRXN3 encodes a member of the neurexin family of which NRXN1 is associated with Pitt-Hopkins-like syndrome 2 (MIM 614325) and ACOT1 is involved in lipid metabolism." (PMID 28327206, 2017). "In addition, Pten, Shank3, Adnp, and Nrxn1 are associated with Cowden syndrome, Phelan-McDermid syndrome, Helsmoortel-Van der Aa syndrome, and Pitt-Hopkins-like syndrome 2, respectively." (PMID 39431203, 2024). "Defects in NRXN1 gene have been identified in cases diagnosed as Pitt-Hopkins-like-syndrome 2 (PTHLS2; OMIM#614325)." (PMID 39655047, 2024).
Anxiety (8 papers, 2013 to 2023). Intense feelings of nervousness, tension, or panic often arise in response to interpersonal stresses. "In conclusion, we have provided the first evidence that deletion of the Nrxn1 gene in mice leads to alterations in social behaviours, as well as locomotor activity, anxiety, normal home cage behaviours and aggression." (PMID 23840597, 2013). "Thus, the reduced expression of Nrxn1 and Nlgn1 in mutant mice could contribute to the changes in anxiety and activity, as we report here." (PMID 37238646, 2023). "Together, the absence of significant alterations in locomotor or anxiety-related behaviors in these Nrxn1 mouse models provides a behavior control and allows us to appropriately interpret other motor-related behavioral phenotypes." (PMID 36848371, 2023).
attention deficit-hyperactivity disorder (8 papers, 2020 to 2026). A disorder characterized by a marked pattern of inattention and/or hyperactivity-impulsivity that is inconsistent with developmental level and clearly interferes with functioning in at least two settings (e.g. at home and at school). "Individuals with NRXN1 deletions also show symptoms of attention deficit hyperactivity disorder (ADHD)." (PMID 31812984, 2020).
nicotine dependence (8 papers, 2010 to 2026). Physical and psychological dependence on nicotine. "A meta-analysis of genome-wide linkage scans also confirmed the association of NRXN1 with nicotine dependence." (PMID 24465966, 2014). "A genome-wide association study first posited a role for NRXN1 in nicotine dependence." (PMID 24465966, 2014). "There are differences in the genotype frequencies of SNPs in genes related to nicotine metabolism (CYP2A6) and nicotine dependence (NRXN1, DRD4, CHRNA3-CHRNA5)." (PMID 34205269, 2021). "Previously, we had reported other SNPs in smoking-related genes as NRXN1, DRD4, HTR2A, CHRNA3, CHRNA5, and CYP2A6 in Mexican mestizo, focused on smokers enrolled in a smoking cessation program, mostly with high tobacco consumption and nicotine dependence." (PMID 34205269, 2021).
Alzheimer disease (7 papers, 2019 to 2023). A progressive, neurodegenerative disease characterized by loss of function and death of nerve cells in several areas of the brain leading to loss of cognitive function such as memory and language. "Non-gonosomal genes that were differentially regulated between sexes included an upregulation of NRXN1 in female oligodendrocytes, which has previously been linked to Alzheimer’s disease and multiple sclerosis, and of HIF3A in female OPCs which is related to oxidative stress." (PMID 37217978, 2023). "Finally, the synaptic protein neurexin-1 (NRXN1), a potential biomarker of neurodegeneration in Alzheimer’s disease, was found to be consistently decreased after TBI compared to control." (PMID 36482407, 2022). "Gene-based analyses implicated AGXT2 and CALN1 for VL, while analyses of protein-protein interactions implicated synaptic proteins previously associated with Alzheimer disease biology, SYT9 and NRXN1 for VSTM; ZFAND5, GRIK2, and ZC3H18 for VL; and PRLHR for paragraph recall." (PMID 35974141, 2022).
depression (7 papers, 2019 to 2026). "The relationships of mutations and expression of the NRXN1 gene published in the literature confirm its importance in neurodevelopmental and neuropsychiatric disorders so this may be a significant indication of its importance in depressive disorders." (PMID 34357104, 2021). "The purpose of the study was also to investigate the role of the NRXN1 gene in the etiology and epigenetics of depression." (PMID 34357104, 2021). "In the further part of the study, it was shown that the occurrence of depression and the expression of the NRXN1 gene at the mRNA level were significant predictors of the expression of the NRXN1 gene at the protein level." (PMID 34357104, 2021). "This study showed that the expressions of the NRXN1 gene at both mRNA and protein levels in patients with recurrent depressive disorders significantly differ from the expressions of this gene in the health control group." (PMID 34357104, 2021). "The scientific literature contains no specific research results and scientific reports about expression of the NRXN1 gene in the group of patients diagnosed with depressive disorders." (PMID 34357104, 2021). "Regarding NRXNs, some authors have pointed out that the expression of the NRXN1 gene may play an important role in depressive disorders." (PMID 39061976, 2024). "Due to this fact, the aim of the study was to verify the expression of gene NRXN1 at the mRNA and protein level in patients suffering from depression versus healthy controls, as well as to search for clinical variables related to expression of the analyzed gene." (PMID 34357104, 2021). "A statistically significant result is obtained which indicated that the presence of depression and expression of the NRXN1 gene at the mRNA level are significant predictors of expression of the NRXN1 gene at the protein level (p = 0.001; standard error BETA = 0.058; confidence interval = 0.95)." (PMID 34357104, 2021). "In order to assess which factors significantly influenced expression level of the studied gene in the groups, a regression analysis was performed for expression of NRXN1 at the protein level with two predictors—expression of NRXN1 at the mRNA level and depression morbidity (group)." (PMID 34357104, 2021). "Gene expression of NRXN1 at both mRNA and protein levels may play an important role in the etiopathogenesis of depressive disorders and these expressions significantly differ from the expressions of these genes in healthy people." (PMID 34357104, 2021). "Finally, in one study, a rat chronic mild stress model of depression was used to determine if neurexin expression was altered in major depressive disorder; however, no change in neurexin 1, 2 or 3 levels was observed." (PMID 34610269, 2021).
Tourette syndrome (7 papers, 2013 to 2023). A neurologic disorder caused by defective metabolism of the neurotransmitters in the brain. "Additionally, both Neurexin 1 and Netrin 4 have also been implicated in the etiology of Tourette syndrome." (PMID 34207710, 2021).